TLR9 (toll like receptor 9)
Diseases named in the same sentence as TLR9 in open-access papers (continued):
Sharing a sentence is not in itself a finding about the gene and the disease.
inflammation (30 papers, 2007 to 2026). Aberrant reaction of the microcirculation characterized by movement of fluid and leukocytes from the blood into extravascular tissues. "Pld4-deficient mice have inflammatory disease and an exaggerated TLR9 response, while Pld4- and Pld3-knockdown mice die before the age of 21 days due to lethal liver inflammation." (PMID 37979047, 2024). "In addition, the inhibition of the toll-like receptor 9 (TLR9) present in the list has been recognized to promote a kind of cardiac inflammation using a mouse model of TLR9-deficient (TLR9-D)." (PMID 33525692, 2021). "This study investigates the unexplored role of STAT1, a transcription factor in pathogen-driven immune responses, in mediating TLR9-induced liver inflammation." (PMID 41561071, 2026). "We identified that TLR9-induced liver inflammation is dominated by a monocyte population differentiating into Mφs, which we termed transitioning monocytes." (PMID 41561071, 2026). "Here, we demonstrate that both type I and II IFN-induced STAT1 activation drives murine TLR9-induced systemic, and in particular, liver inflammation." (PMID 41561071, 2026). "Our study represents the first study to examine the in vivo role of TLR9 from myeloid cells in mtDNA-mediated lung inflammation." (PMID 36674451, 2023). "Recent study showed phages from active UC patients induced more IFN-γ via a TLR9-dependent pathway, which is linked to aggravated intestinal inflammation and colitis, suggesting that certain phages may trigger intestinal inflammation in the gut and contribute to IBD." (PMID 32601832, 2021). "TLR9 plays an important role in acetaminophen-induced liver inflammation, and we recently reported that ammonia along with DNA induces neutrophil TLR9 expression in patients with acetaminophen-induced ALF and advanced hepatic encephalopathy." (PMID 31401214, 2019). "Intestinal inflammation induced in mice by TNBS downregulates the intestinal expression of FXR in a TLR9-dependent manner." (PMID 23372731, 2013). "In the current study, we show for the first time that TLR9−/− mice exhibit a low bone mass and low-grade systemic chronic inflammation, which is characterized by the expansion of CD4+ T cells and increased levels of inflammatory cytokines, including TNFα, RANKL, and IL1β." (PMID 35624094, 2022). "Moreover, the mtDNA-mediated pulmonary inflammation was related to the TLR9 pathway, confirmed by using TLR9-/- mice and TLR9 antagonist ODN2088." (PMID 32292516, 2020). "The results suggested that the TLR9-p38 pathway might play an essential role in the induction of lung inflammation by CBNPs or mtDNA." (PMID 32292516, 2020). "TLR9 inhibition could decrease both pancreatic IL-1β expression and lung inflammation in experimental AP15." (PMID 28754974, 2017). "Because macrophages play a role in resolution of inflammation, reduced levels of TNFα along with increased numbers of macrophages may indicate a pro-inflammatory role for TLR9 in lung inflammation induced following exposure to chicken barn air." (PMID 27375768, 2016). "Looking at clinical manifestations, for instance, the CFA stimulation model and IL1RN deficiency/Tsc2 KO models may be more suitable for studying chronic and arthritic subtypes of SJIA, while the repeated TLR-9 model may be preferable for studying lung inflammation." (PMID 36964620, 2023). "In addition, other danger signal receptors independently of STING or TLR9 may be activated leading to type I IFN/IFNAR-dependent pulmonary inflammation including MDA5/RIG-l, TLR4/MyD88, TLR7MyD88 or TLR8/MyD88,)." (PMID 31619733, 2019). "We have previously demonstrated that sensitization to allergens, with a TLR4 or TLR9 agonist, prevents the development of Th2 lung inflammation without shifting the lung inflammation towards a Th1/Th17 pattern." (PMID 34358159, 2021).
renal disease (11 papers, 2013 to 2025). "TLR9 rs5743836 (T1237C) expression is also associated with a higher risk of renal disease and premalignant gastric disease induced by H. pylori." (PMID 40149591, 2025). "By 30 weeks of age, Tlr9-deficient MRL/+ had more severe renal disease, increased T cell activation, and higher titers of anti-Sm and anti-RNA autoantibodies than Tlr9-intact animals, as had been the case in the MRL.Faslpr model." (PMID 28278279, 2017). "Expression of TLR9(T1237C) is also linked to relative risk for H. pylori-induced premalignant gastric disease and renal disease." (PMID 26361369, 2015). "Thus, TLR7 deficiency exclusively in B cells is sufficient to ameliorate the exacerbated renal disease observed in MRL/lpr mice globally deficient for TLR9." (PMID 37606042, 2023). "This TLR7-TLR9 paradigm might be explained by the more pathogenic RNA containing immune complexes in TLR9 deficient mice that deposit in the kidneys leading to more severe renal disease." (PMID 35096904, 2021). "Epithelial-to-mesenchymal transition (EMT), leukocyte infiltrations, and inflammatory responses were explored in this study to provide more evidence for TLR-9 mechanisms during kidney disease." (PMID 33644078, 2021). "Our previous studies, in which EE was administered via silastic subcutaneous implants, supports a role for estrogenic chemicals in promotion of renal disease, and a role for EE in the suppression of TLR9 cytokine production." (PMID 32251357, 2020). "Pristane exposed TLR9-deficient BALB/c mice had an exacerbated production of autoantibodies against RNA, neutrophil cytoplasmic antigens, and myeloperoxidase and worse renal disease than TLR9-sufficient mice." (PMID 31354738, 2019). "TLR9-deficieny in MRL.Fas(lpr) mice caused exacerbated renal disease which was abrogated in the absence of IFNAR-signaling through specific reduction of anti-RNA specific antibodies, suggesting a crucial role of TLR7-IFNα signaling axis in SLE pathogenesis." (PMID 31354738, 2019). "Recent studies also suggest that the changes in TLR9 expression may have an effect on renal disease development in SLE." (PMID 22948541, 2013). "Activation of TLR-9 induces progression of renal disease in MRL-Fas (lpr) mice." (PMID 23472199, 2013). "Toll-like receptor 9 (TLR-9) a receptor for CpG DNA is involved in activation of immune cells in renal disease and may contribute to chronic inflammatory disease progression through an interleukin-6 (IL-6) dependent pathway." (PMID 23472199, 2013). "There is emerging evidence that TLR-9 may play an important role in renal disease and a number of inflammatory conditions of other organ systems." (PMID 23472199, 2013). "However whether a TLR-9/IL-6 signal amplification loop such as that which regulates B cell proliferation is active in patients with renal disease remains to be investigated." (PMID 23472199, 2013). "To further explore the roles of TLR-9 in kidney diseases, especially chronic diseases, in this study, we utilized a traditional AKI→CKD transition rodent model to further explore the biological effects of TLR-9 on renal disease." (PMID 33644078, 2021). "We also evaluated the clinical parameters of kidney disease in mice stimulated in vivo with imiquimod (a TLR7 agonist as a surrogate for viral exposure) and ODN 2395 (a TLR9 agonist, as a surrogate for bacterial exposure)." (PMID 32251357, 2020). "yaa mice had decreased anti-nucleosome IgG titers but more severe renal disease when Tlr9 was absent." (PMID 28278279, 2017).
kidney (9 papers, 2017 to 2024). "Previous animal experiments have found that JP inhibits the TLR9 signaling pathway in the kidney, exerts its anti-inflammatory effect, and reduces kidney damage." (PMID 35591863, 2022). "In this study, we found that the addition of a class A TLR9 agonist (ODN1585) enhanced the effectiveness of anti–PD-1 ICB in reducing colorectal peritoneal metastases." (PMID 36278484, 2022). "Endogenous extracellular histones activated the NLRP3 inflammasome in macrophages through TLR9, which triggered sterile inflammation during liver IR injury." (PMID 32666684, 2020). "Here, we demonstrated that the class A TLR9 agonist, ODN1585, markedly enhanced the efficacy of anti–PD-1 therapy in mouse models of colorectal peritoneal metastases." (PMID 36278484, 2022). "mtDNA can be recognized by Toll-like receptor 9 (TLR9) and cystosolic Cgas-stimulator of interferon genes (STING) and activate the inflammasome, leading to kidney inflammation and fibrosis." (PMID 35053290, 2022). "Furthermore, depleted TLR9 levels restrained NF-κB viability and NLRP3 expression and reduced kidney inflammation, microalbuminuria discharge, blood sugar level, and glomerular damage in experimental mice (db/db) kidneys." (PMID 35120573, 2022).
immune diseases (8 papers, 2012 to 2023). "We determined whether ammonia-induced brain edema and immune dysfunction are mediated by TLR9 and if this could be prevented in a TLR9-deficient mouse model." (PMID 31401214, 2019). "TLR9 in lysozyme expressing cells was critical for the development of brain edema and immune dysfunction." (PMID 31401214, 2019). "Surprisingly, however, TLR9 deficiency in the presence of normal TLR7 function reduces only anti double-strain-DNA autoantibody levels, but not other autoantibodies and is associated with a more severe AI disease, suggesting a regulatory role of TLR9 for TLR7-mediated immune disease." (PMID 22826712, 2012). "This process of immune dysfunction following traumatic injury is dominated by the pattern recognition receptors TLR2, TLR4 and TLR9." (PMID 37108280, 2023).
cardiovascular diseases (4 papers, 2014 to 2025). "Previous studies have identified that TLR9‐related signalling pathways are involved in the pathophysiological development of many cardiovascular diseases." (PMID 33140921, 2020). "As a member of the Toll‐like receptor family, TLR9 has already been shown to play a vital role in inflammation and cardiovascular diseases." (PMID 33140921, 2020). "Altered cardiac Toll-like receptor 9 (TLR9) signaling is important in several experimental cardiovascular disorders." (PMID 25126740, 2014). "This should be considered in future studies on the pathophysiological significance of TLR9 in cardiovascular diseases." (PMID 25126740, 2014). "Altered TLR9-signaling has pathophysiological significance in various experimental cardiovascular disorders." (PMID 25126740, 2014). "Altogether, TLR9 signaling in cardiovascular disease exhibits a dual nature." (PMID 39158380, 2025).
hematological malignancies (4 papers, 2018 to 2025). "Here, we explore the multifaceted roles of TLRs in hematological malignancies, with TLR9 serving as a prime example of the diverse impact of TLRs on the occurrence of hematological tumors." (PMID 40922674, 2025). "The majority of clinical trials using TLR agonists to treat hematological malignancies have focused on TLR3, TLR7/8, and TLR9." (PMID 36476317, 2022). "Therefore, TLR9-targeted delivery of STAT3 inhibitors, as single agents or in combination with T cell-based approaches, offers a novel strategy for safer and more effective immunotherapy of BCL and, potentially, other hematologic malignancies." (PMID 29433938, 2018).
metabolic disorders (4 papers, 2019 to 2025). "Therefore, there appears to be some potential dynamic between IL-33 and the TLR system, specifically TLR3 and TLR9, during the development of metabolic disease, which may be impacted by glucose-lowering medications." (PMID 31073344, 2019).
neurodegenerative disease (3 papers, 2021 to 2022). A disorder of the central nervous system characterized by gradual and progressive loss of neural tissue and neurologic function. "Dysregulation of TLR9 signalling has been associated with several autoimmune and neurodegenerative diseases." (PMID 34409288, 2021).
peripheral neuropathy (3 papers, 2020 to 2021). A disorder affecting the peripheral nervous system. "Also, Toll-like receptor 9 in macrophage is involved in chemotherapy-induced peripheral neuropathy in male but not female mice." (PMID 33424538, 2020).
cardiac disease (2 papers, 2019 to 2025). "TLR9 has a wide variety of functions in cardiac disease, so further research is needed to determine the risks and benefits of TLR9 as a therapeutic target and to access the method of application." (PMID 31160091, 2019). "While TLR9‐mediated energy modulation in the myocardium offers cellular protection against cardiac injury, TLR9‐driven inflammation can be detrimental, underscoring the complex and context‐dependent role of TLR9 in heart disease." (PMID 39158380, 2025).
myopathies (2 papers, 2018 to 2025). "Thus, it seems that loss of fusion is sufficient to induce mtDNA-mediated TLR9 inflammation in muscle cells that can drive myopathy, a mechanism that may explain the phenotype of the patient harbouring the Q367H variant." (PMID 40175090, 2025). "In summary, we observed elevated mtDNA-mediated TLR9/NF-κB and cGAS-STING inflammatory signalling in a patient harbouring the uncharacterized MFN2 Q367H variant who displayed late-onset myopathy as a standalone phenotype." (PMID 40175090, 2025). "As elevated inflammation can cause myopathy, our findings linking the Q367H MFN2 variant with elevated TLR9 and cGAS-STING signalling can explain the patient’s myopathy." (PMID 40175090, 2025). "Notably, a recent study showed that inducible muscle-specific loss of MFN1 causes mtDNA release via early endosomes, leading to activation of TLR9/NF-κB inflammation and myopathy." (PMID 40175090, 2025). "We found a significant increase in the mRNA expression levels of TLR7 and TLR9 in LMNA-RM muscles, when compared to controls and to other forms of myopathies such as FSHD." (PMID 29895224, 2018). "Arguing that activation of TLR9-mediated inflammation is a general response to loss of mitochondrial fusion, loss of the inner mitochondrial membrane fusion protein OPA1 in muscle leads to TLR9-mediated NF‐κB activation (but not cGAS-STING), where it also drives an inflammatory myopathy." (PMID 40175090, 2025).
brain disease (1 paper, 2022). "Several other innate immune PRRs, such as TLR2, TLR4 and TLR9, have been implicated in the pathogenesis of bacterial, and specifically pneumococcal, brain disease, but in most cases in isolated cell culture conditions." (PMID 36028511, 2022).
TLR9 also shares sentences with these, for which no sentence is quoted: Encephalopathy (6 papers); Fever (4); Hodgkins lymphoma (4); idiopathic pulmonary fibrosis (4); blood cancer (3); chronic kidney disease (3); follicular lymphoma (3); hematological cancers (3); interstitial nephritis (3); Multiple Organ Failure (3); mycoses (3); nasopharyngeal carcinoma (3); neurological disorder (3); paracoccidioidomycosis (3); peanut allergy (3); viral disease (3); allergic conjunctivitis (2); Behcet disease (2); cerebral amyloid angiopathy (2); chlamydia (2); chronic hepatitis (2); chronic periodontitis (2); chronic rhinosinusitis (2); chronic viral hepatitis (2); dermatomyositis (2); eczema (2); Epstein-Barr virus infection (2); Hypercholesterolemia (2); kidney failure (2); Lewis lung carcinoma (2).
A further 126 diseases each share a sentence with TLR9 in 2 papers or fewer.